IL17A (interleukin 17A)
Diseases named in the same sentence as IL17A in open-access papers (continued):
Sharing a sentence is not in itself a finding about the gene and the disease.
infection (continued). "An additional study performed to assess dose-response effects of GW9662 on IL-17 production revealed that increasing concentrations of GW9662 during infection significantly upregulated colonic IL-17A mRNA expression." (PMID 23469071, 2013). "In our model of early primary RSV infection, neutrophil infiltration occurred within 48 hours post-infection, effectively ruling out local production of IL-17A that requires adaptive immune processes." (PMID 24194936, 2013). "IL-17A and IL-17F are produced during H. pylori infection and Th17 cells contribute to control of infection and to chronic inflammation in many models of H. pylori disease." (PMID 23533678, 2013). "6-week old BALB/c mice were given intra-peritoneal injections of 50 μg anti-IL-17A or isotype control antibody at both two days prior to intranasal infection and upon infection with RSV." (PMID 24194936, 2013). "We found here that NKp46+ cells expanded in the vagina in infection and produced IL-22, more than IL-17A, likely via AhR." (PMID 23853597, 2013). "We found significant increase in the frequency and absolute numbers of IL-17A-producing CD4 T cells in the lung throughout the course of infection with B. pertussis." (PMID 23592988, 2013). "Consistent with this, il12a, il12b, ifng, il6, il17a mRNA expression were considerably increased in the brains of P. berghei ANKA-infected Alox5-KO vs. WT mice at 5 days after infection." (PMID 23613965, 2013). "To directly prove the role of IL-22, we evaluated levels of IL-22, as well as of companion cytokines, such as IL-17A and IL-17F, in infection and the consequences of IL-22 inhibition or administration." (PMID 23853597, 2013). "Numerous studies have identified a protective role of IL-17A in immunity against various infections, including the infection of intracellular and extracellular bacteria, fungi, and even parasites." (PMID 23956759, 2013). "After infection with Mtb, the proliferation of IL-17A-producing cells is dependent on IL-23, which mediates protective mechanisms in the absence of IL-12." (PMID 23460846, 2013). "In contrast, the rate of bacterial clearance was dramatically slower in IL-17A−/− mice, with 100 fold more bacteria on day 3 and significant bacteria in the lungs on day 10, when the WT mice had cleared the infection." (PMID 23592988, 2013). "Immunophenotyping results showed a pronounced increase of IL-17A- and IFNγ-producing cells in the gastric LP after 30 and 60 days post-infection." (PMID 24039925, 2013). "Early after infection of C57BL/6 mice with Mtb real time RT-PCR of lung homogenates was conducted to compare gene expression of Il22 with the expression of Il17a, Il17f, Il12b, and Il23p19." (PMID 23460846, 2013). "We had previously reported that mice defective in IFN-γR develop disseminating lethal infection following primary challenge with B. pertussis, and here we show that the bacterial burden and clearance is also significantly compromised in IL-17A−/− mice." (PMID 23592988, 2013). "In the lung, γδT cells have been demonstrated to be the major source of early IL-17A production in response to some infections, such as K. pneumonia, M. tuberculosis, and Mycobacterium bovis." (PMID 23956759, 2013). "Early studies in murine infection models have established IL-17A derived from Th17 cells and IL-17-producing CD8+ T (Tc17) cells as important regulators of host defense against extracellular bacteria such as Klebsiella pneumoniae." (PMID 23383714, 2013). "Early IL-17A production by these innate cells provides an initial response to pathogens to recruit neutrophils within 4–8 hours after infection." (PMID 23956759, 2013). "The expression patterns associated with these different profiles suggest that Th1 and Th17 cells are slightly more susceptible to infection with the studied R5-tropic reporter virus, as virus-infected cells express more IFN-γ and IL-17A than other cytokines." (PMID 22876188, 2012).
infection (continued). "IL-17A induces the infiltration of neutrophilic granulocytes at the infection site, as well as the expression of proinflammatory mediators such as IL-6, CXC chemokines, and matrix metalloproteinases." (PMID 23056325, 2012). "After 8 hours of infection, at the more acute phase, the virulent strain had induced an extensive increase in many cytokines, particularly IL-22, IL-17A and IL-17F (132 to 233 fold)." (PMID 22675469, 2012). "Protection was associated with the induction of Th1-type and pro-inflammatory cytokine responses and IL-17A production early during infection in protected animals." (PMID 23216912, 2012). "Production of IL-17A and IL-17F by cells from the spleen and lymph nodes of infected mice peaked by days 10–20 post-infection and gradually decreased by day 32 post-infection." (PMID 22577359, 2012). "By contrast, infection resulted in increased expression of IL-17A in TLR2−/− mice, compared to all other infected groups throughout the time course, and was associated with the specific increase in neutrophil influx in this group." (PMID 22724018, 2012). "Strikingly, on day 1 post-infection FVB mice exhibited systemic IL-17A (78 pg/ml) while levels remained undetectable in C57BL/6 mice." (PMID 23300439, 2012). "Depletion of these cells leads to abrogation of the enhanced IL-17A production observed upon depletion of neutrophils during infection with the protective C. neoformans strain H99γ." (PMID 23216912, 2012). "In conclusion, the data presented herein describe the identification of the γδ+ T cell as a significant source of IL-17A in the lungs of neutropenic mice during infection with C. neoformans strain H99γ." (PMID 23216912, 2012). "At 6 h after Cm infection, only the wells with combined IL-17A and IFN-γ stimulation showed measurable iNOS mRNA expression, but not those with single cytokine." (PMID 22745717, 2012). "At 24 h and 36 h after infection, the mRNA expression of iNOS were measured in all groups but the expression in the TC-1 cells treated by the combination of IL-17A and IFN-γ was significantly higher than others." (PMID 22745717, 2012). "Greater expression of IFNG and IL17A were detected in DBA/2 mice at day 15 post-infection using the Mouse Common Cytokines Gene Array." (PMID 23006927, 2012). "Beyond the known inflammatory mediators, we identified IL-22, IL-17A and IL-17F as highly upregulated cytokines and as first responders to infection during the innate phase of the host immune response." (PMID 22675469, 2012). "We observed a significant increase in IL-17A within lung homogenates derived from IL-17RA−/− mice compared to wild-type mice on day 7 post-infection with C. neoformans strain H99γ." (PMID 23216912, 2012). "those that are highly upregulated by infection of both the virulent and avirulent strains (IL-22, IL-17A, IL-17F and iNOS); and iv." (PMID 22675469, 2012). "This time point was chosen because it is the time point at which pulmonary IL-17A production is at its peak during infection with C. neoformans strain H99γ." (PMID 23216912, 2012). "The combination of IL-17A with IFN-γ induced higher level of iNOS activity than IFN-γ alone in a dose-dependent manner at 36 h after infection." (PMID 22745717, 2012). "In contrast, depletion of neutrophils in combination with γδ+ T cells resulted in a significant reduction in pulmonary IL-17A compared to IL-17A detected in lung homogenates of mice depleted of neutrophils alone on day 7 post-infection." (PMID 23216912, 2012). "Similar plasma concentrations of IL-17A were observed within AE patient groups and infection-free controls." (PMID 22969818, 2012). "In the current studies, we further explored the role of neutrophils and IL-17A production in mice during infection with C. neoformans strain H99γ." (PMID 23216912, 2012). "We sought to determine the population responsible for the increased production of IL-17A in the lungs of neutrophil depleted mice on day 7 post-infection with C. neoformans strain H99γ." (PMID 23216912, 2012).
infection (continued). "IL-17A was also shown to be produced very early by γδ T cells triggering protective immunity against infection exacerbating chronic inflammation." (PMID 21858022, 2011). "Our studies examining IL-17A expression within lung leukocytes during C. neoformans strain H99γ infection suggest that neutrophils are the predominant source of IL-17A, rather than CD4+ T cells, which has been shown in other systems." (PMID 21359196, 2011). "These discoveries highlight the importance of the IL17A gene on infection and, in particular, on Gram-positive and fungal infections." (PMID 22026963, 2011). "Intranasal infection with GAS-2W induced IL-17A-producing 2W:I-Ab-specific T cells; whereas intravenous and subcutaneous inoculations induced IFN-γ-producing cells." (PMID 21966268, 2011). "Mice treated with anti-IL-17A antibody had significantly increased pulmonary fungal burden compared to mice treated with the isotype control antibody (P<0.002) at day 7 post-infection." (PMID 21359196, 2011). "Previous results in our laboratory have shown that IL-17A production in IFN-γ KO mice is similar to that observed in WT mice following infection with C. neoformans strain H99γ." (PMID 21359196, 2011). "Following intranasal inoculation with GAS-2W, antigen-experienced 2W:I-Ab-specific CD4+ T cells were identified in the nasal-associated lymphoid tissue (NALT) that produced IL-17A or IL-17A and IFN-γ if infection was recurrent." (PMID 21966268, 2011). "Such cells include Th17-cells, capable of producing large amounts of the cytokines IL-17A and IL-22 which facilitate cellular recruitment to sites of infection and enhance the release of antimicrobial products from local epithelium." (PMID 22003400, 2011). "Pulmonary cytokine production in IL-17A depleted mice during infection with C. neoformans strain H99γ." (PMID 21359196, 2011). "The acquisition of IL-17A production by 2W:I-Ab-specific T cells and the capacity of mice to survive infection depended on the innate cytokine IL-6." (PMID 21966268, 2011). "In response to infection with Candida albicans, IL-17A, IL-17F and IL-17RA were up-regulated in mucosal tissues." (PMID 22174673, 2011). "We observed a significant reduction in IL-17A production in lung homogenates of mice treated with the anti-IL-17A antibody at days 7 and 14 post-infection compared to mice treated with the isotype control antibody." (PMID 21359196, 2011). "The peak of IL-17A production appears early during sub-lethal infection, it precedes the peak of immune activation and the nadir of the disease, and then subsides subsequently." (PMID 20585449, 2010). "Taken together, these observations provide evidence that IL-17A is indeed produced in the lungs in response to inhalational LVS infection, and in accordance with other observations." (PMID 20585449, 2010). "Both innate and adaptive T cell-immunity to C. jejuni infection led to the release of IFNγ, IL-22 and IL-17A; suggesting a critical role for this cytokine triad in establishing host anti-microbial immunity during the acute and effectors phase of infection." (PMID 21085698, 2010). "Evidence of Th17 subset activity through IL-17A mRNA expression was found predominantly in the LGT at the later time points of infection." (PMID 21079691, 2010). "The co-induction of IFN-γ2 and IL-17A/F2 during infection with T. carassii suggests the presence of mixed Th1/Th17 phenotypes in T. carassii-infected fish." (PMID 20885956, 2010). "Here we provide direct and substantial evidence for the involvement of IL-17A in host defense to inhalational LVS infection." (PMID 20585449, 2010). "The potential beneficial effect of exogenous administration of IL-17A was tested in a model of lethal infection with 10×LD50." (PMID 20585449, 2010). "The expression of IL-17A was analyzed in total lung single cell suspensions along the course of sub-lethal infection." (PMID 20585449, 2010).
infection (continued). "In order to directly test the in vivo role of IL-17A in the response to sub-lethal LVS infection, IL-17A was depleted in vivo using anti-IL17A antibodies." (PMID 20585449, 2010). "NK cells are the principal cellular source of IFN-γ in the lungs following infection while γδ T cells are the major producers of IL-17A." (PMID 21085613, 2010). "During infection IL-17A, can induce multiple pro-inflammatory cytokines, chemokines and antimicrobial effectors." (PMID 21124903, 2010). "Infection with 100×LD50 significantly enhanced IL-17A production as compared to infection with 0.1×LD50, when measured on day 2 (B2-B3)." (PMID 20585449, 2010). "LVS infection resulted in a distinct increase in IL-17A+ producing cells both in CD4+ T and γδ T cell populations." (PMID 20585449, 2010). "Remarkably, a robust and early induction of IL-17A production by γδ T cells was observed as early as day 2-post infection, and reached the peak by day 6 (40% of the γδ T cells, data not shown) (A3)." (PMID 20585449, 2010). "IL-17A was detected only in some cells within the Lymphocyte Gate, an expression that increased during the course of infection." (PMID 20585449, 2010). "The efficacy of IL-17A depletion was determined by measuring IL-17A in the BALF of mice 6 days post intranasal infection with 0.1×LD50 and intraperitoneal administration of the neutralizing antibody, or of PBS as control." (PMID 20585449, 2010). "The depletion of IL-17A also exacerbated disease manifestations, evident mainly following infection with 30 CFU." (PMID 20585449, 2010). "Since γδ T cells were identified as an early source for IL-17A during LVS infection, their role in the response to LVS was tested." (PMID 20585449, 2010). "In contrast, IL-17A production in sub-lethal infection reached a peak on day 4 that rapidly subsided, concurring with the observed transient mRNA induction." (PMID 20585449, 2010). "However, accumulating evidence has revealed that IL-17A also plays critical roles in immune responses, infection immunity, tissue regeneration, and neural repair." (PMID 40536951, 2026). "Excessive activation of IL‐17a signaling in the gut following maternal pregnancy infection leads to malformations in fetal cortical development and affects chromatin accessibility of naive CD4+ T cells, leading to fetal neurodevelopmental disorders and severe intestinal inflammation." (PMID 40027477, 2025). "In addition, we observed significant changes in the levels of IFN-γ, IL-4, and IL-17A during the early stages of infection, while the inhibitory cytokine IL-10 exhibited a significant increase in the later stages." (PMID 40742129, 2025). "However, systemic IL-17A blockade carries infection risks, necessitating targeted delivery approaches." (PMID 40867579, 2025). "Cytokine levels decreased for 6 of 9 assayed cytokines or the chemokine in the Chr7x3 AAB variant (IL-17a, IL-22, IL-5, IFN-γ, TNF-α, and IL-1β) and further decreased for all cytokines and the CXCL1 chemokine in the Chr7x3 ABB variant when compared to infection with Chr7x2 SC5314." (PMID 40577316, 2025). "Furthermore, MHV68 infection leads to increased IL-17A production in the lungs during the acute stage of infection and the spleen and peritoneal cavity during the chronic stage of infection by multiple cell types." (PMID 41335125, 2025). "Levels of IL-17A and IL-4 were unaffected by infection or CX3CL1 receptor inhibition." (PMID 40936920, 2025). "Furthermore, the concentration of IL-17A, a key cytokine in host protective immunity to infection secreted for example by TH17 cells, was elevated in the plasma of denatonium-treated Trpm5+/+ mice compared to controls but not in plasma of Trpm5−/− mice." (PMID 39794305, 2025). "Notably, Th1 and Th17 subsets remained stable after infection, supported by the unchanged expression of their signature transcriptional regulators (tbx21 and rorc) and effector cytokines (ifng and il17a/f1)." (PMID 40821846, 2025).
infection (continued). "Though interleukin 17A (IL-17A, commonly known as IL-17) has garnered significant interest due to its pro-inflammatory role, it plays varying roles depending on the tissue, contributing to health during responses to injury, physiological stress, and infection." (PMID 40563358, 2025). "In animals with rapid recovery, elevated IL-17A concentration may reflect a prompt and effective immune activation that contributes to infection clearance." (PMID 40703922, 2025). "Interestingly, our study revealed an increased IL-17A transcription by CD8αα+hi γδ T cells particularly at later time points post infection, when innate immune defenses to control bacterial invasion were already advanced." (PMID 40438105, 2025). "In our previous report, based on an unbiased transcriptome analysis, we found that the Th17 cell differentiation-related pathway was enriched in PmA-infected lungs, implying that Th17 cells and their downstream factor IL-17A may be involved in PmA infection." (PMID 41402924, 2025). "IFN-γ and IL-17A cooperate to prevent S. aureus outgrowth during craniotomy infection." (PMID 39989461, 2025). "Cytokine levels decreased for 6 of 9 assayed cytokines or the chemokine in the Chr7×3 AAB variant (IL-17a, IL-22, IL-5, IFN-γ, TNF-α, and IL-1β) and further decreased for all cytokines and the CXCL1 chemokine in the Chr7×3 ABB variant when compared to infection with Chr7×2 SC5314." (PMID 39896449, 2025). "At 7 days post infection (dpi), gene expression analysis revealed elevated transcription of the activation marker IL-2Rα and proinflammatory cytokines (IL-17A, IFN-γ) in CD8αα+hiCD4-TCR1- cells from γδ T cell knockout chickens compared to CD8αα+hi γδ T cells from wild-type birds." (PMID 40438105, 2025). "No clear differences in the changes in relative abundance during infection were observed between mouse strains for the small Il17a-expressing T cell Il17 cluster; the T cell CD4 Foxp3 cluster, likely reflecting regulatory T cells; or the CD8 T cell and NK/ILC1 clusters." (PMID 40986319, 2025). "Importantly, Tbet−/− mice exhibited a robust population of IL-17A producing CD4 T cells at 3 weeks post infection, confirming that Tbet prevents Th17 differentiation during Mtb infection." (PMID 40463021, 2025). "We next investigated whether exogenous IL-17A treatment provides protection against WT Mtb infection during primary infection." (PMID 40463021, 2025). "However, excessive numbers of Th17 cells or IL-17A can induce autoimmune diseases and promote infections." (PMID 41402924, 2025). "While CD8αα+hiCD4-TCR1- cells are present in low numbers in wild-type chickens, in our study they may compensate for the loss of γδ T cell-derived IL-17A in TCR Cγ−/− chickens through both numerical expansion and early activation post infection." (PMID 40438105, 2025). "At the higher inoculum, WT and tlr4 mutant mice exhibited significantly increased levels of IL-1α, IFN-γ, TNF-α, MCP-1, IL-1β, IL-6, and IL-17A early during infection relative to the lower inoculum while levels dissipated by 7 dpi, consistent with bacterial clearance." (PMID 40817088, 2025). "Additionally, high expression of IL-17A, a cytokine that aids in neutrophil infiltration to the infection site, was observed in both APP-EVs- and Coglapix-immunized groups." (PMID 39831520, 2025). "Conversely, iBALT still developed in Il17a and Il17f double-knockout mice following infection with modified vaccinia virus Ankara, indicating that the requirement for IL-17 in iBALT formation may be context-dependent." (PMID 41029827, 2025). "However, secondary infection significantly decreased the absolute number of CD4 + IL17A + T cells in C. auris-infected mice." (PMID 40294061, 2025). "Furthermore, as for KC/GRO, there was a significant interaction between the infection with P. aeruginosa and the Scnn1b-Tg genotype on IL-17A levels, demonstrating a synergistic effect of these parameters on the neutrophil-attractant chemokine." (PMID 40512037, 2025).